RET (ret proto-oncogene)
Diseases named in the same sentence as RET in open-access papers (continued):
Sharing a sentence is not in itself a finding about the gene and the disease.
ovarian carcinoma (9 papers, 2015 to 2025). A malignant neoplasm originating from the surface ovarian epithelium. "RET inhibitor approved for specific gene mutations; its use in ovarian cancer is under investigation." (PMID 40141188, 2025). "The identification of the gain-of-function RET mutations in EOC highlights the potential use of RET in targeted therapy to treat ovarian cancer patients." (PMID 32293499, 2020). "Our study identified the oncogenic role of RET mutations in ovarian cancer and provided a potential treatment option for ovarian cancer patients with RET mutations." (PMID 32293499, 2020). "Epithelial ovarian cancer sequencing projects identify recurrent genomic RET missense mutations in 1.98% of patients, ranking as the top-five hit among the 100 receptor tyrosine kinases-encoding genes." (PMID 32293499, 2020). "We studied the oncogenic functions of RET mutations and tested the therapeutic effects of vandetanib in ovarian cancer." (PMID 32293499, 2020). "To obtain a comprehensive view of RET mutations in ovarian cancer, we also collected RET mutations from other sequencing databases, including COSMIC, ICGC and CCLE." (PMID 32293499, 2020). "To investigate whether vandetanib has the potential to be applied in ovarian cancer patients with RET mutations, we tested the inhibitory effects of vandetanib on A2780 cells expressing the R693H or A750T mutant." (PMID 32293499, 2020). "Next, we demonstrated that the kinase inhibitor vandetanib could effectively inhibit the viability of ovarian cancer cells with RET mutations." (PMID 32293499, 2020). "The biological and clinical significance of RET genomic aberrations in ovarian cancer context are investigated by a series of in vitro and in vivo experiments." (PMID 32293499, 2020). "In conclusion, R693H and A750T mutants of RET enhance the signal transduction of RET, the cell viability and colony formation of cells, and the growth of tumor xenografts of ovarian cancer." (PMID 32293499, 2020). "However, additional studies are required to determine the therapeutic utility of RET inhibition in ovarian cancers." (PMID 35957881, 2022). "The development of next-generation selective RET inhibitors such as BLU-667 and LOXO-292 may contribute to the precision therapy of patients with RET-mutant ovarian cancer." (PMID 32293499, 2020). "The RET-MAPK signaling pathway might be the main mechanism by which RET mutants promote the development of ovarian cancer." (PMID 32293499, 2020). "First, we collected and analyzed data on RET mutations in EOC from genomic databases and found the oncogenic effects of RET mutations on promoting cell viability and colony formation of ovarian cancer cells in vitro and accelerating tumor xenograft growth of ovarian cancer in vivo." (PMID 32293499, 2020). "Our results showed that RET R693H and A750T mutants could promote the viability, colony formation and activation of the RET-MAPK and RET-AKT signaling pathway in ovarian cancer, and the RET inhibitor vandetanib could significantly decrease cell viability and signal transduction at 500 nM." (PMID 32293499, 2020). "RET mutants significantly enhance the activation of RET and its downstream MAPK and AKT signaling pathway in ovarian cancer cells." (PMID 32293499, 2020). "In our study, we identified the genes with a mutation frequency ranking in the top 5 of 100 PTK genes in EOC, namely, MST1R, INSR, RET, PDGFRB, and PTK7, among which we studied the overlooked oncogenic role of RET in ovarian cancer." (PMID 32293499, 2020). "We believe that, in the future, therapies targeting RET will prolong survival while not influencing the quality of life of patients with RET-mutant ovarian cancer." (PMID 32293499, 2020).
Parkinson disease (9 papers, 2013 to 2026). A progressive degenerative disorder of the central nervous system characterized by loss of dopamine producing neurons in the substantia nigra and the presence of Lewy bodies in the substantia nigra and locus coeruleus. "Notably, alterations in RET have been implicated in Parkinson’s disease, suggesting its significance in the pathogenesis of this neurodegenerative disorder." (PMID 37761940, 2023). "Genetic defects in genes encoding docking proteins have the potential to cause abnormal interaction with the RET signaling, which in turn may result in aging neurons and contribute to aging-related disorders such as Parkinson's disease and Alzheimer's disease." (PMID 24036517, 2013). "Targeting RET and/or GFRα with small molecules may resolve the problems associated with using GFLs as drugs and can result in the development of therapeutics for disease-modifying treatments against Parkinson’s disease and neuropathic pain." (PMID 32556722, 2020). "BDNF and GDNF were studied therapeutically in models of Parkinson disease (PD) and Huntington disease (HD), with loss of neurons that express TrkB and RET." (PMID 31244606, 2019). "Quantitative fluorescent intensities demonstrated that the levels of RET were 1.5–2.0 times higher in Parkinson’s disease with combined delivery than Parkinson’s disease controls while they were 0.27–0.71 times lower following delivery to the putamen alone." (PMID 32203581, 2020). "Our key results show that baculovirus-produced non-mammalian GDNF and GFRα1 stimulate human RET phosphorylation as well as signal through the MAPK/ERK cascade to promote the survival of dopaminergic neurons affected by Parkinson’s disease." (PMID 28467503, 2017). "We also compared RET expression in CERE120-treated Parkinson’s disease cases, non-gene treated Parkinson’s disease cases, and age-matched non-Parkinson’s disease control brains." (PMID 32203581, 2020).
renal agenesis (9 papers, 2010 to 2024). Renal agenesis (RA) is a form of renal tract malformation characterized by the complete absence of development of one or both kidneys (unilateral RA or bilateral RA respectively), accompanied by absent ureter(s). "Paradoxically, mutations causing both activation and inactivation of the RET proto-oncogene have been linked to renal aplasia, emphasizing the importance of the precise control of RET in kidney development." (PMID 39594614, 2024). "Mutations in the receptor tyrosine kinase RET gene are also more commonly found in the spectrum of congenital urinary anomalies like renal agenesis and aplasia." (PMID 38077999, 2023). "Another study demonstrated that stillborn fetuses with renal agenesis or severe dysplasia had a high positive rate (30%) of disease-causing mutations, although only RET, GDNF, and GFRA1 genes were evaluated." (PMID 32164334, 2020). "In addition, mutation of RET can also lead to ureteral bud hypoplasia, renal agenesis, distal nephron dysplasia, and failure of the urinary system to develop." (PMID 36408280, 2022). "RET is a proto-oncogene, and mutations in this gene can cause renal agenesis." (PMID 33126852, 2020). "Furthermore, many other mutant genes that cause renal agenesis exert their effects via the GDNF/RET pathway." (PMID 20084103, 2010). "In their study, the authors have demonstrated how RET-null organoids fail to undergo branching and exhibit a phenotype like renal agenesis." (PMID 38077999, 2023). "For instance, in OHVIRA the CHD1L, TRIM32, RET, and WNT4 genes may be associated with renal agenesis." (PMID 39594614, 2024). "Other genes that have been identified in bilateral renal agenesis include ANOS1, EYA1, and RET." (PMID 39594614, 2024). "In contrast to Gdnf or Ret mutations, renal agenesis caused by concomitant lack of the transcription factors ETV4 and ETV5 is not rescued by removing Spry1, consistent with their role downstream of both RET and FGFRs." (PMID 20084103, 2010).
Cowden syndrome (8 papers, 2016 to 2025). "Classical risk factors for pediatric PTC include prior radiation exposure, familial syndromes (e.g., familial adenomatous polyposis, Cowden syndrome), and certain genetic mutations such as RET/PTC rearrangements and B-type RAF kinase (BRAF) mutations." (PMID 40821173, 2025). "RET, PTEN, or NF1 mutations were detected to screen for MEN2B, Cowden syndrome, or NF1, respectively." (PMID 35783634, 2022).
familial hypocalciuric hypercalcemia (8 papers, 2020 to 2025). Familial hypocalciuric hypercalcemia (FHH) is a generally asymptomatic genetic disorder of phosphocalcic metabolism characterized by lifelong moderate hypercalcemia along with normo- or hypocalciuria and elevated plasma parathyroid hormone (PTH) concentration.
hereditary cancer syndrome (8 papers, 2020 to 2024). "MEN2 is a hereditary cancer syndrome caused by RET proto-oncogene mutations involving multiple endocrine organs, including the thyroid and adrenal glands." (PMID 37761273, 2023). "Multiple Endocrine Neoplasia 2 (MEN2) is a hereditary cancer syndrome for developing medullary thyroid cancer (MTC) due to germline mutations of RET gene." (PMID 34771717, 2021).
Apert syndrome (7 papers, 2012 to 2025). Apert syndrome (AS) is a frequent form of acrocephalosyndactyly, a group of inherited congenital malformation disorders, characterized by craniosynostosis, midface hypoplasia, and finger and toe anomalies and/or syndactyly.
metastatic carcinoma (7 papers, 2017 to 2025). A carcinoma which has spread from the original site of growth to another anatomic site. "Finally, mutational analysis by sequencing 10,000 metastatic cancer patients revealed that co-occurrence of hTERT mutations and RET mutations occur more frequently than expected when all tumors are considered." (PMID 36142729, 2022). "Given the important role that mutant RET plays in metastatic cancers, significant efforts have been made in developing inhibitors against RET kinase activity." (PMID 35957881, 2022).
pituitary adenoma (7 papers, 2015 to 2024). "This connection between AIP and RET has implications for the aggressive pituitary adenomas observed in the majority of affected patients with AIP mutations and could be of future use in alternative therapeutic approaches." (PMID 34588620, 2021). "Known pheo/PGL genes (SDHA-D, SDHAF2, RET, VHL, TMEM127, MAX, FH) and pituitary adenoma genes (MEN1, AIP, CDKN1B) were sequenced using next generation or Sanger sequencing." (PMID 25494863, 2015). "Interestingly, pituitary adenomas are not a classical feature of MEN2, and there have been only four reports in the literature presenting individuals with an association between pituitary adenomas and RET variants, with only two of them bearing both corticotropinomas and RET variants." (PMID 39512978, 2024).
acute myeloid leukemia (6 papers, 2012 to 2025). Acute myeloid leukemia (AML) is a group of neoplasms arising from precursor cells committed to the myeloid cell-line differentiation. "Activating mutations of Ret have been linked to cancer, i.e., somatic chromosomal rearrangements result in Papillary Thyroid Carcinoma, point mutations of RET lead to Multiple Endocrine Neoplasia 2 syndrome and RET is also differentially expressed in acute myeloid leukaemia." (PMID 23300832, 2012).
chronic myelomonocytic leukemia (6 papers, 2014 to 2020). A myelodysplastic/myeloproliferative neoplasm which is characterized by persistent monocytosis, absence of a Philadelphia chromosome and BCR/ABL fusion gene, fewer than 20 percent blasts in the bone marrow and blood, myelodysplasia, and absence of PDGFRA or PDGFRB rearrangement. "Increasingly, deep sequencing approaches on a wider variety of tumors are identifying less frequent RET rearrangements in other cancer types including chronic myelomonocytic leukemia and colorectal, breast, ovarian and head and neck tumors." (PMID 30666215, 2018). "In a single study, rare RET rearrangements have been found in patients with the myeloproliferative disorder, chronic myelomonocytic leukemia." (PMID 30666215, 2018). "Finally, in patients affected by myeloproliferative disorders (MPD), such as chronic myelomonocytic leukemia or primary myelofibrosis, oncogenic RET fusions with BCR or FGFR1OP genes were identified." (PMID 26046350, 2015). "RET has vast implications in human diseases and is commonly discovered in the forms of gain-of-function and loss-of-function mutations and gene fusions, resulting directly in human pathogenesis such as Hirschsprung disease, papillary thyroid cancer (PTC) and chronic myelomonocytic leukemia (CMML)." (PMID 31105873, 2019).
head and neck cancer (6 papers, 2018 to 2025). A primary or metastatic malignant neoplasm affecting the head and neck. "It is worth noting that the A883V RET mutation detected in CC has been previously reported in head and neck cancer, suggesting a role for RET activation in the development of CC." (PMID 29854313, 2018). "Furthermore, melatonin can induce RET in complex I. The induced RET increased ROS generation via modification of CoQ redox and mitochondrial membrane potential in head and neck cancer cells to facilitate their apoptosis." (PMID 40847302, 2025). "Indeed, RET testing is currently used in routine in next-generation sequencing (NGS) panels, which identified 2% of RET alterations in various types of cancer, including digestive, breast, ovarian, and head-and-neck cancers." (PMID 39139787, 2024).
Lynch syndrome (6 papers, 2016 to 2024). An autosomal dominant hereditary neoplastic syndrome characterized by the development of colorectal carcinoma and a high risk of developing endometrial carcinoma, gastric carcinoma, ovarian carcinoma, renal pelvis carcinoma, and small intestinal carcinoma. "Other, less common, gene mutations include CHEK2, PALB2, CDH1, MLH1 (associatedwith Lynch syndrome), and RET." (PMID 38993971, 2024). "In agreement with the concept of eventual regional variants and/or population heterogeneity, we have previously reported novel mutations in other genes in our population, detected by direct sequencing such as protooncogen RET, Lynch Syndrome, APC in Familial Adenomatous Polyposis." (PMID 28947987, 2017). "No Lynch syndrome was observed in patients with RET mutation." (PMID 34741450, 2021).
neuroendocrine carcinoma (6 papers, 2019 to 2025). A malignant neuroendocrine neoplasm composed of cells containing secretory granules that stain positive for NSE and chromogranin. "To determine if RET inhibition triggers adaptive resistance in other RET mutant cellular contexts we tested two MTC cell lines, a neuroendocrine cancer associated with activating mutations in RET." (PMID 35510953, 2022). "Consistently, RET signaling is deregulated in several neural crest–associated diseases, mostly in neuroendocrine cancers." (PMID 31015297, 2019).
acromegaly (5 papers, 2015 to 2024). Acromegaly is an acquired disorder related to excessive production of growth hormone (GH) and characterized by progressive somatic disfigurement (mainly involving the face and extremities) and systemic manifestations. "To our knowledge, we report the first acromegaly patient carrying a RET pathogenic variant: c.2410G>A (rs79658334), p.Val804Met." (PMID 38339173, 2024). "Our case describes a new phenotype associated with the RET pathogenic variant, represented by aggressive acromegaly, and suggests consideration for RET mutation screening if NGS for well-established PitNET-associated gene mutations renders negative." (PMID 38339173, 2024). "Six cases of 3PA have been linked to germline defects in MEN1 (four cases) and the RET proto-oncogene (two cases), with one case of acromegaly associated with MEN1 and another with RET." (PMID 39194755, 2024). "In acromegaly, every gene involved in the two RET pathways—particularly glial cell-derived neurotrophic factor (GDNF)—is specifically enriched." (PMID 39194755, 2024). "To explore if human AIP-FIPA somatotroph adenomas also conserved the RET-GDNF pathway, we performed studies in two directions." (PMID 34588620, 2021). "This has implications in pituitary pathology as demonstrated for the role of RET and GFRα4 in acromegaly tumors." (PMID 33071961, 2020). "Within the adenopituitary, somatotrophs express both RET and GFRα1, together with GDNF and this is maintained in somatotroph-derived pituitary tumors causing acromegaly." (PMID 33071961, 2020). "Recently, a case of acromegaly with an RET mutation was described, occurring in the absence of other phenotypic manifestations typically associated with RET mutations." (PMID 39194755, 2024). "One possible treatment for resistant acromegaly (in general) is Sorafenib, an RET inhibitor, which acts by blocking GDNF/AKT serine/threonine kinase 1 survival action through protein kinase AMP-activated catalytic subunit alpha 2 and prevents cell death without changing the RET apoptotic pathway." (PMID 39194755, 2024). "Our present results indicate that this approach with anti-RET kinase inhibitors could even be more successful for treating the FIPA somatotroph adenomas that are so aggressive and resistant to surgery and the usual medical therapy with agonists." (PMID 34588620, 2021). "We performed immunohistochemistry for RET (total RET, HPA008356), GDNF and GFRα1 comparing five sporadic (Sp GH) and five AIP+ somatotroph adenomas." (PMID 34588620, 2021).
anaplastic cancer (5 papers, 2007 to 2020). "Some studies have underscored that RET rearrangements are associated with the lack of transformation of PTC into poorly differentiated or anaplastic carcinoma." (PMID 23326755, 2012). "Tumors harboring RET/PTC, especially RET/PTC1, have a very low probability of progression to poorly differentiated and anaplastic carcinomas." (PMID 22654559, 2011).
autoimmune thyroid disease (5 papers, 2008 to 2024). Inflammatory disease of the thyroid gland due to autoimmune responses leading to lymphocytic infiltration of the gland. "The other patient with an RET mutation had unilateral PCC, autoimmune thyroiditis, and type 1 diabetes mellitus." (PMID 33584544, 2020).
Cachexia (5 papers, 2018 to 2024). Severe weight loss, wasting of muscle, loss of appetite, and general debility related to a chronic disease. "One possible explanation for a worse survival of GDF15+GFRAL+RET-coexpressing GC patients could be cancer-associated cachexia." (PMID 34149933, 2021). "GDF15-GFRAL-RET regulates metabolic homeostasis, particularly under stress conditions, but may also promote cancer associated anorexia or cachexia, suggesting that blocking RET signals may have added benefit in reducing weight loss associated with other forms of therapy." (PMID 30666215, 2018). "Through the activation of the GFRAL (GDNF-family receptor α-like)-RET (Rearranged during Transfection) signaling pathway, GDF15 can induce weight loss, making it a potential target for treating cachexia." (PMID 39172988, 2024).